MIR6886 (microRNA 6886)
Synonyms: hsa-mir-6886
Gene: MicroRNA gene on chromosome 19 (11,113,474 to 11,113,534, forward strand). Ensembl gene ENSG00000284553.
Homologues: Orthologues: chimpanzee MIR6886 (100% identical).